ATRX (ATRX chromatin remodeler)
Diseases named in the same sentence as ATRX in open-access papers (continued):
Sharing a sentence is not in itself a finding about the gene and the disease.
glioma (continued). "The inclusion of more patients with IDH1/2 and ATRX mutations in the low-risk group and more patients with EGFR mutations in the high-risk group indicates that BM-gene-related risk scores can distinguish glioma patients with different prognoses." (PMID 36292695, 2022). "Furthermore, the data from WB, qRT-PCR, and immunofluorescence assays revealed that FADD expression was inhibited in TMZ-resistant glioma cells by ATRX by promoting the trimethylation of histone H3K27 in the FADD promoter region." (PMID 36348274, 2022). "Interestingly, a recent study demonstrated that ATRX loss promoted malignant and immunosuppressive phenotypes of IDH1 mutant glioma cells." (PMID 35720326, 2022). "On the contrary, ATRX and DAXX mutations are mutually exclusive in glioma and other cancers." (PMID 35406561, 2022). "Loss of ATRX was observed in 16 H3K27M mutant gliomas and 17 H3K27M wildtype gliomas." (PMID 35756637, 2022). "We found that patient-derived GBM cells harboring somatic ATRX mutations are also more sensitive to RTK and PDGFR inhibitors, supporting that high-grade glioma patients harboring ATRX mutations could respond better to these drugs." (PMID 35406561, 2022). "In order to decipher whether ATRX-deficient cells are sensitive to PDGFRi, we assessed the sensitivity of MOG-G-UVW, U-251, and SF-188 (EV and ATRX KO) high-grade glioma cell lines to the potent and selective PDGFRi, CP-673451." (PMID 35406561, 2022). "Meanwhile, ATRX mutant gliomas also showed significantly decreased DDR score." (PMID 35720326, 2022). "Finally, we observed more deletions of a chromatin modifier, ATRX, in AYA gliomas where ATRX deletions and mutations were mutually exclusive, suggesting this gene is haplo-insufficient." (PMID 36433963, 2022). "However, only the RTKi pazopanib led to increased toxicity in ATRX KO high-grade glioma cells compared to the WT counterparts." (PMID 35406561, 2022). "Although there is evidence of spatiotemporal consistency in TERTp and ATRX mutations in gliomas, changes in the TMM have not been thoroughly documented using longitudinal samples of human cancer." (PMID 35953846, 2022). "BRDs also have an immunomodulatory role in ATRX-deficient, IDH-mutant gliomas." (PMID 36212415, 2022). "Unfortunately, there are no standard criteria for what constitutes loss of ATRX staining in gliomas." (PMID 34458259, 2021). "Loss of ATRX expression and the presence of ALT are significantly correlated in gliomas." (PMID 34069193, 2021). "Additionally, DDX60 favored its expression in mesenchymal and classical subtype, MGMT unmethylated (P < 0.001), ATRX wild-type (P < 0.001), TERT promoter mutated (P < 0.001), and IDH wild-type gliomas (P < 0.001)." (PMID 34178649, 2021). "Thus, the correlation between increased NFI gene expression and motif usage that we had observed in human ATRX-mutant gliomas is conserved in ATRX-KO murine tumors." (PMID 34763709, 2021). "In the case description, we present the immunohistochemistry and pathologic characteristics identifying the tumor as an anaplastic oligodendroglioma, IDH-mutant, 1p/19q codeleted, with ATRX expression isolated within a vast majority of areas that were lower-grade glioma." (PMID 34335443, 2021).
glioma (continued). "Likewise, ATRX-mutant patient-derived glioma cells were found to be more resistant than a wild-type control to senescence induced by Temodar, Imatanib, Doxorubicin, or CDKi treatment, in an IDH1-mutant background." (PMID 34763709, 2021). "We did not detect any loss of ATRX expression in WHO IV gliomas, but in 2/3 of anaplastic gliomas, which is congruent with current literature." (PMID 33094355, 2021). "Similarly, transcription-factor regulators (e.g., ZEB1) and enhancers (e.g., TNC) of invasion were significantly increased both in human ATRX-mutant and ATRX-KO murine glioma specimens." (PMID 34763709, 2021). "Moreover, we reasoned that some of these differences would be conserved and regulated by ATRX in murine gliomas as well." (PMID 34763709, 2021). "Both IDH-A and ATRX-KO glioma show significantly increased expression of FYN." (PMID 34763709, 2021). "Therefore, ATRX-KO IDH1R132H murine glioma phenocopies the glial regulatory program observed in IDH-A." (PMID 34763709, 2021). "Therefore, we included an extensive work up including the differentiation of high-grade versus low-grade gliomas and ATRX, IDH1/2, 1p19q, MGMT in our analysis." (PMID 34944806, 2021). "However, previous work has shown that, in fact, loss of ATRX is generally insufficient to trigger ALT in most cells, with the notable exception of a minority of glioma cell lines." (PMID 34828344, 2021). "Age, sex, IDH mutation status, ATRX mutation status, 1p/19q co-deletion status, promoter methylation status of MGMT, radiation therapy history, gliomas type, and risk score were significantly related to OS in the TCGA cohort based on the results from the univariate analysis." (PMID 34136486, 2021). "Mukherjee and colleagues showed that the combination of ATRX loss and IDH1 R132 mutation might be sufficient for ALT activation in gliomas." (PMID 34069193, 2021). "In IDHwt GBMs, maintenance of the telomeres is mainly achieved through mutations of the TERT promoter, while in IDH-mutated (non-codeleted) gliomas, ATRX alteration is frequently observed." (PMID 32642724, 2020). "The process is similar to evaluation of ATRX staining in gliomas." (PMID 32051040, 2020). "For example, H3.3K27M but not H3.1K27M gliomas have a significantly increased frequency of ATRX mutations." (PMID 32902381, 2020). "As with ATRX, DAXX mutations have been found in glioma and pancreatic neuroendocrine tumors." (PMID 32533344, 2020). "Moreover, we verified for the first time that ATRX is a downstream target of miR-1269a and mediates its biological functions in glioma." (PMID 33194637, 2020). "Unlike ependymoma, L1CAM protein expression was not correlated with the C11orf95-RELA fusion gene in other gliomas, but it had correction with the patient age (older than 45-year-old, p = 0.006), ATRX mutation (p = 0.003) and Ki67 (p = 0.007)." (PMID 32509846, 2020). "ATRX inactivation outlines the characteristic phenotypes of glioma-derived cells." (PMID 33194637, 2020).
glioma (continued). "Interestingly, a study on gliomas arising in neurofibromatosis 1 (NF1) found the same frequent CDKN2A and ATRX genetic alterations in NF1 high-grade gliomas." (PMID 31677015, 2020). "Taken together, these findings support the notion that G4-mediated DNA damage induces specific patterns of CNAs in the ATRX-deficient, IDHmut-noncodel glioma subtype, which in turn influence malignant evolution." (PMID 30808951, 2019). "ATRX, the most commonly mutated among them (in 37% of diffuse gliomas), forms a complex with DAXX and histone 3 variant H3.3, the genes frequently mutated in pediatric gliomas." (PMID 30644073, 2019). "Moreover, recent work has shown that ATRX-mutant gliomas in particular exhibit increased sensitivity to DNA-damaging combinations of IR and chemotherapy." (PMID 30808951, 2019). "These two cell lines are intriguing models for the future study of ATRX loss and ALT in glioma." (PMID 30226859, 2018). "Considering the established role of ATRX as an epigenetic regulator, we hypothesized that its inactivation induces glioma-relevant phenotypes by way of chromatin remodeling and downstream shifts in gene expression." (PMID 29535300, 2018). "Furthermore, of all included factors, senior glioma patient, PLP2 overexpression, loss of ATRX, and positive expression of AxL, NUR77 or PDGFRA were the independent prognostic factors under cox regression analysis." (PMID 30373180, 2018). "Specifically, gliomas are divided into IDH-mutant (IDHmt) and IDH-wild type (IDHwt), IDHmt further subdivided to the ones bearing 1p/19q codeletion and ones with the ATRX (ATP-dependent helicase ATRX, X-linked helicase II) mutation." (PMID 31435515, 2018). "For patient ≥ 55 years, only those with a history of a preexisting lower grade glioma, those with midline location (in which “diffuse midline glioma, H3 K27M” has not been discarded) and those with known ATRX mutation should be sequenced." (PMID 29086250, 2018).
glioma (continued). "In addition, in vitro analysis of ATRX knockdown in glioma cells inhibited cell migration, increased cell death, and reduced cell viability." (PMID 29034211, 2017). "The only other known driver gene mutated in LCIS was ATRX, frequently mutated in neuroblastoma, low-grade glioma and glioblastoma but not common in breast cancer." (PMID 28095868, 2017). "Furthermore, the role of ATRX in tumorigenesis, specifically gliomas, is comprehensively elucidated." (PMID 29034211, 2017). "Again, results are different from glioma as we found a low prevalence of loss of ATRX (5.6%), without any correlation to IDH mutation status in chondrosarcoma." (PMID 28484589, 2017). "The ATRX status is one of the critical markers that define the molecular classification of gliomas." (PMID 29034211, 2017). "However, we found highly frequent ATRX inactivation (∼92.9%) in TERT wild-type gliomas, and there was a significantly inverse relationship between TERT promoter mutations and ATRX inactivation." (PMID 26556853, 2016). "Among 70 cases of 1p/19q non-codeleted gliomas examined for ATRX expression, internal positivity was detected in 61 cases and only 26.2% (16/61) of cases demonstrated ATRX loss." (PMID 27556304, 2016). "In support of this conclusion, it has been recently shown that ATRX deficiency impairs non-homologous end joining and increases sensitivity to DNA damaging agents in a glioma mouse model." (PMID 27602331, 2016). "Our results provided novel insights into ATRX-related regulatory functions at the DNA methylation and mRNA expression level in astrocytic tumors, and here could serve as important resources for future dissection of ATRX role in glioma." (PMID 25971279, 2015). "Mutations in the ATRX gene were not identified; this gene is frequently mutated in other glioma subtypes including WHO grade II-III astrocytomas (71 %), oligoastrocytomas (68 %) and secondary glioblastomas (57 %)." (PMID 25694352, 2015). "Although no single molecular marker was associated with tumor grade, we find that tumor grade is correlated with the overall mutational load: grade II gliomas harbour fewer genetic changes than grade III or IV, even within defined molecular subtypes (e.g. ATRX mutated gliomas)." (PMID 26699864, 2015). "In contrast to gliomas of adult patients, ATRX mutations are very rare in pediatric anaplastic gliomas and low-grade gliomas and have to date never been found in pilocytic astrocytomas." (PMID 24559763, 2014). "The impact of ATRX as prognostic marker in low-grade gliomas is to date still unclear." (PMID 24559763, 2014). "In conclusion, ATRX seems to be a promising candidate biomarker in gliomas, which could help to refine, in combination with IDH and 1p/19q status, the prognosis of patients with malignant gliomas." (PMID 24559763, 2014). "Finally, imaging features specific to glioma subtypes and molecular genetic features, such as ATRX and 1p/19q status, as well as metabolomics indicators like phenylalanine, 2-glyceryl phosphate, lysine, and N-acetylaspartic acid (NAA), were not included in this study." (PMID 40548110, 2025). "In particular, the absence of ATRX mutations contrasts with its well-documented role in lower-grade gliomas and astrocytomas, implying that alternative mechanisms, such as chromatin remodeling defects, might be involved in tumor progression." (PMID 40282990, 2025).
glioma (continued). "Additionally, certain IDH–wild-type gliomas also harbor ATRX alterations." (PMID 41422096, 2025). "The CT2A glioma line extensively leveraged in this work may already harbor intrinsic tumor-related molecular mechanisms independent of ATRX loss and mutant IDH1 that may impact immune microenvironmental engagement." (PMID 38272925, 2024). "Interestingly, further data show the development of ALT without ATRX loss in a subgroup of pediatric high-grade gliomas introducing germline variants in mismatch repair (MMR) genes as the possible cause of increased occurrence of ALT in these patients." (PMID 38240992, 2024). "Interestingly, none of the cases had mutations in either TERT or ATRX, indicating they are mutually exclusive in MM, similar to those observed in gliomas." (PMID 37649078, 2023). "Given H3.3/ATRX co-localize with PML, and PML-NBs are a known oncogenic driver in acute promyelocytic leukemia, we asked if the H3.3/ATRX mutations might be affecting the PML pathway in pediatric gliomas." (PMID 38066546, 2023). "This suggests that CNS cancers with IDH1/ATRX deficiency are not subject to the same DNA lesions or repair processes as other CNS cancers and they may potentially belong to a separate patient subclass, though we could not identify evidence of this." (PMID 36883553, 2023). "Grade 4, GBM, ATRX loss, no radiotherapy, and no chemotherapy are all malignant factors in gliomas." (PMID 36468012, 2022). "Unlike the signatures of TERTp mutation and ATRX loss, which are mutually exclusive in gliomas, and contrary to our expectation, the TMM groups could not be predicted by TERTp mutation or ATRX loss." (PMID 35953846, 2022). "Growing evidence shows that some gliomas harbor neither TERTp nor ATRX mutations." (PMID 35953846, 2022). "The GSEA analysis indicated that mutation of gene ATRX was related to “humoral immune response”, and now it has been reported in many tumors including pleomorphic Sarcomas, glioma, gastric cancer patients, while the relationship between mutation of ATRX with cytochrome P450 was not reported." (PMID 36531058, 2022). "Whether the high-grade gliomas arising in the setting of NF1 occur de novo or from transformation of a pre-existing low-grade glioma following acquisition of additional oncogenic drivers (e.g., CDKN2A deletion, ATRX mutation) remains uncertain." (PMID 35945463, 2022).